REST (RE1 silencing transcription factor)
Diseases named in the same sentence as REST in open-access papers (continued):
Sharing a sentence is not in itself a finding about the gene and the disease.
tumor (continued). "Taken together, these data suggest that the vascular effects induced by REST KO, rather than an effect on cell proliferation, resulted in the reduced tumor growth and metastatic potential." (PMID 32486064, 2020). "Two out of three tumor samples were positive for REST staining, whereas REST was absent in normal brain stem samples." (PMID 29435175, 2018). "The seemingly paradoxical role of REST as both a tumor suppressor in non-neural tissue and oncogene in neural tissue demonstrates the complex nature of REST regulation." (PMID 27698411, 2016). "This suppression of REST on NR2B might account for the opposite trend of the expression of spinal REST and NR2B in tumor-bearing mice." (PMID 27732941, 2016). "Indeed, we observe that the tumour cell line HepG2, which displays HIF1A mRNA induction in hypoxia, has lower REST level than HEK293." (PMID 26647819, 2015). "Finally, the minor allele of the SNP rs1040480, located in pRE1-49 within an intron of the tumour-suppressor PTPRT, reduces the affinity of REST." (PMID 22496669, 2012). "Tumors that stain negative for the REST C-terminus correlate strongly with decreased time to disease recurrence, increased tumor size, and a higher number of lymph node metastases, all of which indicate a more aggressive disease course." (PMID 20548947, 2010). "Additionally, data from an analysis of REST and EMT markers’ expression in PCa tumor samples using the GENT2 public database support our findings in the cell culture system, showing a negative correlation between REST expression and Gleason grades, suggesting a role in NEPC risk." (PMID 38542313, 2024). "On the other hand, in non-brain tumours REST plays a tumour suppressor role." (PMID 37301955, 2023). "However, the role of REST in cell proliferation and tumor growth is not consistent depending on cell type." (PMID 36810892, 2023). "REST, the common regulator of the two feed-forward loops, showed a positive association with stromal, immune and ESTIMATE scores whereas a negative association with tumor purity." (PMID 36713370, 2022). "If MBs with REST elevation do indeed mimic endothelial cells, we reasoned that transcription factors directing endothelial specification such as ETS1 may also be expressed in tumor cells." (PMID 33469989, 2021). "Importantly, REST exhibits oncogenic activity in neural environments but has tumor suppressor activity in non-neuronal cells." (PMID 34758854, 2021). "We found that higher REST expression level positively correlated with higher WHO grade (p < 0.001), IDH status-WT (p < 0.001), non-1p/19q codeletion (p < 0.001), histological type-GBM (p < 0.001), tumor status -with tumor (p < 0.001) and primary therapy outcome-PD (p < 0.001)." (PMID 34859007, 2021). "In support of this, the gold-standard ME in the REST mRNA could not be detected following RNase R digestion in any of the healthy or tumor samples, or by RT-PCR, while circLRBA was detectable." (PMID 33207694, 2020). "However, the role of REST in ES growth and the regulation of the tumor vasculature have not been elucidated." (PMID 32486064, 2020). "Comparing the REST‐deficient cells to the wild‐type cell showed a significant increase in the expression of some RE1‐containing genes; however, it did not result in differentiating the tumor stem cell or interrupting the oncogenic regulation." (PMID 32720471, 2020). "REST is a tumour suppressor in non-neuronal cancers of the breast, colon and lung, therefore increasing the range of pathophysiological settings were our findings might be of importance in the regulation of the HIF-1α response and glycolysis." (PMID 26647819, 2015). "However, a role for REST in the regulation of MB tumor microenvironment has not been investigated." (PMID 33469989, 2021).
tumor (continued). "SMARCA4 expression was positively correlated with multiple NE genes including SYP, CHGA, INSM1, DLL3 and NCAM1 and negatively correlated with non-NE factors REST, NOTCH2, and YAP1 in both SCLC cell lines and patient tumor databases." (PMID 39080761, 2024). "Our data showed a significant up-regulation of REST, but not HAR1A in the invasive margin, relative to the tumour core." (PMID 39602392, 2024). "Although REST is the sole transcription repressor reported to have binding sites across C19MC, its expression shows no discernible change in tumor conditions." (PMID 37542643, 2023). "Together, these findings suggest REST as a transcriptional silencer of TUBB3 and that dysfunctional REST, in conjunction with epigenetic modifications in TUBB3 intron 1, may be important mechanisms underlying aberrant TUBB3 expression in tumours of non-neuronal origin." (PMID 35573698, 2022). "Consistently, REST target gene expression was low in the tumors and high in normal cortex, implicating a possible role of REST in HGG tumor transformation through suppression of target gene expression." (PMID 31420543, 2019). "Our data suggest that in the absence of REST, as it occurs in REST-less tumours, there is no repression of HIF1A transcription, therefore positive regulators like NFκB are able to freely drive HIF1A transcription, leading to increased HIF-1α protein expression in hypoxic tumour microenvironments." (PMID 26647819, 2015). "However, REST knockdown in LNCaP cells does not allow a t-NEPC xenograft to develop, supporting the notion that SRRM4-mediated REST gene splicing leads to neuroendocrine differentiation but does not induce proliferation sufficient for clonal expansion and t-NEPC tumor establishment." (PMID 28427194, 2017).
cancer (92 papers, 2007 to 2025). A tumor composed of atypical neoplastic, often pleomorphic cells that invade other tissues. "More studies are warranted to understand the role and underlying mechanism of REST by molecular and cellular approaches for utilizing it as a prognostic marker and a potent therapeutic target against cancer." (PMID 40006989, 2025). "REST has been implicated in a number of pathologies, such as psychiatric disorders, neurodevelopment, and cancer." (PMID 38542313, 2024). "Recently, REST expression was found to be associated with cancer progression, though its exact role in carcinogenesis is uncertain." (PMID 37600577, 2023). "Our study confirms the presence of a neural-related DNA hypermethylation fingerprint in various cancers, of genes linked to neural differentiation, and points to REST as a possible regulator of this mechanism." (PMID 37537688, 2023). "We compared the REST mRNA expression between cancer patients and healthy individuals and analyzed the application prospect and diagnostic significance of the REST expression in KIRC." (PMID 33834072, 2021). "Although the association of REST with various cancer types has been reported, the mechanism by which REST plays a role in cancer progression and tumorigenesis is still unclear." (PMID 33834072, 2021). "In this study, we identified REST as the hub gene of a gene module which is closely associated with cancer stage by weighted gene correlation network analysis." (PMID 31041193, 2019). "The differential sensitivity based on REST activity suggests REST is a promising biomarker to stratify GBM patients into different risk groups for individualized cancer treatments." (PMID 27698411, 2016). "Mutations that compromise REST transcriptional repression have been associated with different cancers, e.g., with childhood renal cancer." (PMID 27289382, 2016). "It will be interesting to examine the expression of AF1Q in these cancers associated with REST dysfunction." (PMID 26341630, 2015). "The pRE1s identified in this study are often located in the vicinity of genes involved in diseases linked to REST mediated mis-regulation, most notably cardiovascular disease, neurological diseases and cancer." (PMID 22496669, 2012). "Aberrant REST expression and function are implicated in diverse disorders including cancer, neurodegeneration and neurodevelopmental diseases." (PMID 19888342, 2009). "In addition, REST expression is positively associated with increased malignant invasion, stages of cancer, and spread to lymph nodes." (PMID 37600577, 2023). "Alternatively, REST may be associated with oncogenesis, as changes in its expression have been associated with several types of cancer." (PMID 36226068, 2022). "Multiples studies have reported the aberrant expression or mutation of REST in different cancers." (PMID 31041193, 2019). "This rather contradictory results may partly explained by the fact that REST has multiple splice variants in different cancers." (PMID 31041193, 2019). "As such, REST controls many cellular processes fundamental to normal physiology and pathological conditions and is implicated in a wide range of human diseases including cancer and neurodegenerative diseases." (PMID 28524599, 2017). "As ∆E3 is modulated by cellular signalling and linked to various types of cancer, we anticipate that ∆E3 contributes to environmentally tuned REST function and may have a broad range of clinical implications." (PMID 28524599, 2017). "Thus, one intriguing possibility is that expression of ion channels in general, including that of IKCa in cancer cells, is linked to regulation by functionally altered REST." (PMID 27289382, 2016).
cancer (continued). "As REST has been previously implicated in a variety of cancers, we decided to look into whether there were any cancer specific REST targets." (PMID 24922058, 2014). "Knock-out of KDM1A (KDM1A-KO) or treatment with KDM1A demethylase inhibitors resulted in the up-regulation of REST along with the suppression of cancer cell growth." (PMID 40006989, 2025). "Because of the high REST gene expression and REST protein levels in the cancer cell lines, REST expression was decreased using reverse transfection and the following functional assays were carried out." (PMID 39273639, 2024). "Nevertheless, decreasing REST expression in EC cell lines increased proliferation, migration, and invasion, which are hallmarks of cancer progression and metastasis." (PMID 39273639, 2024). "The majority of studies on the regulations of REST expression in cancer have been on its protein degradation or alternative splicing." (PMID 38777812, 2024). "This revealed a possible role for REST as mediator of the neural-related hypermethylation fingerprint observed in cancer cells." (PMID 37537688, 2023). "REST expression was analyzed in datasets of The Cancer Genome Atlas (TCGA) and the Genotype-Tissue Expression (GTEx) and validated by the Gene Expression Omnibus and Human Protein Atlas databases." (PMID 36810892, 2023). "Over nearly three decades of research, REST has been revealed to have diverse functions in other tissues such as the heart, pancreas, skin, eye, and vascular, as well as in various cancers." (PMID 37892159, 2023). "The decrease in REST expression can be attributed to the fact that the role of REST in carcinogenesis is complex and depends on the cancer type." (PMID 37600577, 2023). "In an effort to identify cancers in which REST targets were dysregulated, we analyzed gene expression profiling data in TCGA using FireBrowse." (PMID 35177031, 2022). "We therefore wondered if YAP1, like REST, can also modulate cell fate decisions in PNECs in non-cancer contexts." (PMID 35577801, 2022). "The genes assayed were neuroendocrine-associated genes (INSM1, ASCL1, NRCAM, and SNAP25), one gene centered in the gene regulatory network (NUF2), and five possibly cancer-associated genes (PTP4A3, RFC4, REST, APEH, and FBLN2)." (PMID 34395507, 2021). "Recent studies have confirmed that REST is closely related to carcinogenesis and cancer progression." (PMID 33834072, 2021). "Subsequently, we analyzed the diagnostic value of the REST expression in different stages of KIRC, including stage I cancer (AUC = 0.826), stage II cancer (AUC = 0.864), stage III cancer (AUC = 0.906), and stage IV (AUC = 0.901)." (PMID 33834072, 2021). "In particular, BIRC6 and XIAP were positively correlated with REST expression across all cancer types except XIAP in PCPG." (PMID 31964418, 2020). "A unique role for H4K20ac enriched at transcriptional start sites, co-localizing with NRSF/REST to participate in gene repression has been noted in cancer cells." (PMID 33262941, 2020). "Further, IAPs were also highly associated with RE1-silencing transcription factor (REST) expression, an important factor for cancer progression and metastasis." (PMID 31964418, 2020). "It was reported that SRSF3 affected the expression levels of miR-132-3p and miR-212-3p, including both their primary form and their mature form, by controlling RE1-silencing transcription factor (REST) in cancer cells." (PMID 33072610, 2020). "Several studies that modulated REST expression by gene knockdown suggested the direct involvement of REST in reducing cancer cell growth." (PMID 32720471, 2020). "Validation with public database and our own patient samples showed higher expression level of REST in patients with advanced cancer stage." (PMID 31041193, 2019).
cancer (continued). "Next, we investigated the role of REST in EMT as it is the primal step for cancer cells' invasion and metastasis." (PMID 31041193, 2019). "Further actions of REST were found to modify the prognostic evaluations of other cancers, the gliomas." (PMID 31905747, 2019). "Expression level validation of REST in different cancer stages with the TCGA showed higher expression level of REST in advanced stage than early stage." (PMID 31041193, 2019). "In first such studies, the glioblastoma cancer cells, upon silencing of their REST action, stop the G1 phase of their cycle, with ensuing suppression of proliferation and migration." (PMID 31905747, 2019). "REST has been found to be a potent regulator maintaining the self-renewal process of cancer stem cells in GBM and thus a good candidate for therapeutic interventions." (PMID 27698411, 2016). "Subsequent studies showed that HOTAIR directly interacted with both the PRC2 and LSD1/REST/coREST repressor complexes, and in multiple tumor and cancer cell lines, HOTAIR-regulated gene expression enhances tumorigenesis." (PMID 25912306, 2015). "More importantly, we found that REST-003 levels correlate positively with cancer cell invasiveness in several cancer cell lines." (PMID 26053433, 2015). "Here, we used RNA deep sequencing to identify a previously uncharacterized alternatively spliced form of the REST gene, REST-003, that plays a key role in controlling cancer cell invasiveness." (PMID 26053433, 2015). "This is novel as it is the first time that NED of cancer cells has been shown to utilize the REST pathway for autophagy induction." (PMID 24551118, 2014). "As seen in other types of cancer, the low expression of REST in cervical tissues of patients with CIN II/III and ISCC is associated with increased cellular proliferation, inhibition of apoptosis, activation of oncogenic signaling pathways, epithelial–mesenchymal transition, and metastasis." (PMID 41465373, 2025). "Interestingly, high expression of ACSL4 positively correlated with cell survival and proliferation after REST perturbation, based on results of pan-cancer RNAi screen by the DepMap project." (PMID 38609948, 2024). "We were also able to investigate REST expression in two different EC cell lines, one thought to be estrogen-driven and the other being a more aggressive sub-type, and found that REST had more of an impact on estrogen-driven cancer." (PMID 39273639, 2024). "Targeting REST may inhibit cancer stem cell proliferation as REST is crucial for cancer stem cell self-renewal." (PMID 38609948, 2024). "Moreover, REST has been related to various cellular processes involved in cancer progression, and in the case of PCa, it has been directly associated with the epithelial–mesenchymal transition (EMT) process." (PMID 38542313, 2024). "Furthermore, this neural-related hypermethylation fingerprint shows to be relevant in most cancer hallmarks and shows indication to be regulated by the known master neural specification regulator REST." (PMID 37537688, 2023). "We first assessed the REST expression in pan-cancer data of TCGA." (PMID 36810892, 2023). "In summary, our study has revealed a key pathway underlying NE gene upregulation by ADT, as well as established novel relationships between CREB1 and REST, and between EZH2 and REST, which may also have implications in other cancer types and in neurobiology." (PMID 37886478, 2023). "In our study, REST expression showd a decrease in malignant tumors compared to the benign tissues." (PMID 37600577, 2023). "The identification of REST as a potential target for modulation of DNA methylation in cancer highlights the importance of understanding the regulatory network that governs neural-related genes in cancer." (PMID 37537688, 2023). "REST in normal cells contributes to genomic integrity, but in cancer development, it is oncogenic." (PMID 35538578, 2022).